PPT2 (palmitoyl-protein thioesterase 2)
Description:
Catalyzes the cleavage of thioester bonds from S-palmitoyl-CoA or S-palmitoyl-N-acetylcysteamine (unbranched structures) but does not have activity against palmitoylcysteine or palmitoylated proteins, branched structures or bulky head groups. Conversely, hydrolyzes both long and short chain fatty acyl-CoA substrate. [Isoform 2]: Catalytically inactive due to lack of active site His-283.
Synonyms: PPT-2; C6orf8; G14
Tractability: Antibody: UniProt predicts a signal peptide or a membrane-spanning region; its Gene Ontology location is reachable by antibodies, with medium confidence.
Target class: Enzyme; Hydrolase
Gene: Protein-coding gene on chromosome 6 (32,146,580 to 32,163,679, forward strand). Ensembl gene ENSG00000221988.
Subcellular location: Lysosome
Subcellular location (Human Protein Atlas): Golgi apparatus; Vesicles
Pathways (Reactome):
Metabolism: Fatty acyl-CoA biosynthesis
Gene Ontology:
Molecular function: fatty acyl-CoA hydrolase activity; palmitoyl hydrolase activity; thiolester hydrolase activity; long-chain fatty acyl-CoA hydrolase activity
Biological process: fatty-acyl-CoA biosynthetic process; macromolecule depalmitoylation
Cellular component: extracellular exosome; extracellular region; lysosomal lumen; lysosome
Genetic constraint (gnomAD): Loss-of-function variants: 20 observed, 38.96 expected, observed/expected ratio (o/e) 0.51, 90% interval 0.36 to 0.75. The upper end of that interval is the gene's LOEUF score, 0.75, which puts it in group 3 of 6, group 1 being the genes least tolerant of losing a copy. Missense variants: 270 observed, 405.32 expected, observed/expected ratio (o/e) 0.67, 90% interval 0.6 to 0.74. Synonymous variants: 135 observed, 168.67 expected, observed/expected ratio (o/e) 0.8, 90% interval 0.69 to 0.92.
Homologues: Orthologues: macaque EGFL8 (99% identical), chimpanzee PPT2 (99% identical), rabbit PPT2 (97% identical), pig PPT2 (96% identical), dog PPT2 (95% identical), rat Ppt2 (94% identical), guinea pig PPT2 (94% identical), mouse Ppt2 (93% identical), zebrafish ppt2b (60% identical), tropical clawed frog ppt2 (54% identical), zebrafish ppt2a.2 (51% identical), zebrafish ppt2a.1 (49% identical), and 4 more. Paralogues in human: PPT1 (26% identical), DOLPP1 (18% identical).
Diseases named in the same sentence as PPT2 in open-access papers:
PPT2 is named in the same sentence as 12 diseases in open-access papers, as found by Europe PMC text mining. Sharing a sentence is not in itself a finding about the gene and the disease. The quoted sentences say what the papers report.
asthma (2 papers, 2021 to 2025). "Some overlap was detected with DMRs associated with maternal pregnancy asthma status (in gene PPT2; PRRT1) and maternal ever asthma (HOXA genes)." (PMID 40349045, 2025). "We performed a parallel analysis on the PPT2 group (OM‐85 N = 22; placebo N = 20; both groups were comparable in terms of age, gender, BMI and asthma severity)." (PMID 34289183, 2021).
prostate carcinoma (2 papers, 2013 to 2022). A carcinoma that arises from epithelial cells of the prostate gland. "We further explored possible bioactivities of PpT‐2 against prostate cancer cells and bacteria, against which the peptide exerted a moderate antiproliferative effect and negligible antimicrobial activity." (PMID 35460166, 2022).
breast carcinoma (1 paper, 2021). "In agreement with the data generated with transfected-endothelial cells, siRNA-mediated knock-down of PPT1 and PPT2 in the breast cancer cell line MDA-MB-231, which constitutively expresses TF, also reduced fXa-generation." (PMID 34359738, 2021).
emphysema (1 paper, 2025). "A large study using chest CT scans to characterize the distribution and severity of emphysema have found genome-wide associations in the SNRPF and PPT2 regions." (PMID 40579575, 2025).
tumor (5 papers, 2013 to 2024). "ECI2, PPT2, ACSM3, PMVK, and IDO1 were low expressed in the prognosis of high-risk patients, which may be tumor suppressor factors." (PMID 37256178, 2023). "In summary, PPT2 is downregulated in ccRCC, and decreased expression of PPT2 in ccRCC may promote tumor progression by facilitating EMT." (PMID 31956361, 2020). "Weekly treatment of the NOD/SCID mice bearing PPT2- and PC3MM3-induced tumors with the SBT-1214 led to dramatic suppression of tumor growth." (PMID 24086245, 2013).
adenocarcinoma (1 paper, 2013). A common cancer characterized by the presence of malignant glandular cells. "The two larger PPT2-induced SBT-1214-treated residual tumors were also diagnostic of poorly differentiated adenocarcinoma, but possessed a greater degree of nuclear atypia, and only few mitotic figures." (PMID 24086245, 2013).
neurodegenerative disease (1 paper, 2021). A disorder of the central nervous system characterized by gradual and progressive loss of neural tissue and neurologic function. "While PPT1 is associated with neuronal disorders, little is known about the function of PPT2, despite its crucial role in the search for therapeutic solutions against neurodegenerative diseases in humans." (PMID 33670203, 2021).
PPT2 also shares sentences with these, for which no sentence is quoted: cancer (2 papers); Clear Cell Renal Cell Carcinoma (1); neuronal ceroid lipofuscinosis (1); prostate tumor (1); schizophrenia (1).